IL2 (interleukin 2)
Diseases named in the same sentence as IL2 in open-access papers (continued):
Sharing a sentence is not in itself a finding about the gene and the disease.
tumor (continued). "Although CD56brightCD16dim NK cell population possessed less cytotoxicity against tumor as compared to CD56dim NK cell, the present of cytokines especially IL-2 can significantly improved the cytotoxicity of all subtypes of NK cell." (PMID 23800124, 2013). "For example, tumor-bearing animals treated with the E7 DNA vaccine regimen (E7 DNA vaccines+IL-2 cDNA) displayed a 27% tumor cure rate compared to animals treated with E7 DNA vaccines alone (7%)." (PMID 24391824, 2013). "Differentiation of naïve CD4+ T cells into iTreg cells in the periphery is encouraged by tumor antigen in the presence of certain cytokines such as IL-2, IL-10, and TGF-β." (PMID 23378947, 2013). "Specifically, tumor (5 mm)-bearing animals treated with E7 DNA vaccines plus IL-2 cDNA displayed a 50% tumor cure rate, whereas animals treated with E7 DNA vaccines alone or E7 DNA vaccines plus IL-15 cDNA showed 0% and 33% tumor cure rates, respectively." (PMID 24391824, 2013). "A number of therapeutic approaches have been proposed to enhance the anti-tumor effect of suicide gene therapy by inducing an immune response to tumor cells via co-expression of cytokine genes, such as IL-2, IL-2 and TNF-α, IL-12, and IL-21." (PMID 23441198, 2013). "For example, in the pmel-1 T cell receptor transgenic mouse model of adoptive T cell transfer, the exogenous administration of both IL-15 and IL-2 improved the anti-tumor response during the 34 days of follow-up." (PMID 23418547, 2013). "Proliferation of T cells stimulated in the presence of tumor-exosomes was reduced, most pronounced when stimulated by IL2." (PMID 23190502, 2012). "In the case of IL12 and IL2, this produced superior anti-tumor efficacy implying the strategy to muster a broader immune cell response in the combat against cancer." (PMID 23028547, 2012). "The results showed that either resveratrol or IL-2 treatment can induce the expression of FoxO1 in the tumor in vivo." (PMID 22532866, 2012). "In several maligancies, anti-tumor T cell responses, with infiltration of tumors by CD8+ T lymphocytes and local production of interferon-γ and IL-2, have been associated with improved clinical prognosis." (PMID 22279573, 2012). "Since then, many other studies have shown that IL-2 immunotherapy mediated tumor regression via enhanced endogenous tumor specific CD8+ responses." (PMID 23021024, 2012). "In a mouse model of metastatic renal cancer, the use of anti-CD40 agonist mAb in combination with IL-2 or IL-15 can mediate tumor regression by inducing an inflammatory milieu that inhibited intratumoral Treg and MDSC activities." (PMID 22778760, 2012). "By contrast, when this vaccine antigen preparation was administered together with the multiple TLR agonist BCG plus IL-2 and CY (100 μg/dose), a significant inhibition (p < 0.05) of tumor growth was noted (G6)." (PMID 24955288, 2012). "Consistent with the findings with VSV combined with IL-2 and Treg depletion, reovirus/IL-2/CPA cotherapy achieved an activated NK phenotype that achieved significant tumor regression." (PMID 22312364, 2012). "The vaccinated tumor-bearing mice receiving the NKG2D-Fc-IL2 construct demonstrated a significant reduction in tumor mass growth, when compared to the other groups of mice receiving NKG2D-Fc, Con-Fc-IL2, or Con-Fc, or the DNA vaccine alone." (PMID 22509395, 2012). "In line with this, vaccination with staphyloccocus enterotoxin A expressing tumor-exosomes significantly inhibited tumor growth and prolonged the survival time by increasing IL2 and IFNγ secretion and by promoting T helper (Th), CTL and NK activation." (PMID 23190502, 2012). "Taken together, tumor-exosomes affected lymphocyte proliferation, most pronounced in response to IL2." (PMID 23190502, 2012). "Others demonstrated an abscopal effect after manipulation of tumor cells with transgenes expressing several cytokines such as IL-2 or Flt3-L." (PMID 22848871, 2012).
tumor (continued). "The combination of entinostat with IL-2 had a much greater inhibitory effect on tumor growth (∼80% reduction)." (PMID 22303460, 2012). "Further studies have demonstrated that CIK cells, which are lymphocytes induced by many cytokines, have better anti-tumor effects compared with LAK cells (lymphocytes activated by IL-2 alone)." (PMID 23210562, 2012). "In vitro incubation of lymphocytes with IL-2 increased the cytotoxic ability directed against tumour cells." (PMID 23346250, 2012). "In this study, cetuximab treatment significantly inhibited intrathoracic MPM tumor growth, and the addition of IL-2 enhanced this activity." (PMID 22922885, 2012). "IL-2 potently activates and induces NK cell anti-tumor activity, but systemic administration of this cytokine is associated with life-threatening toxicity." (PMID 23316193, 2012). "By introducing rat IL-2 into Clostridium, solid tumours were specifically targeted and sufficient levels of IL2 were produced and excreted to decrease tumours in mice, while avoiding the effects of systemic toxicity." (PMID 22737166, 2012). "In the animal experiment, AFP-DC and IL-2-DC vaccines inhibited the tumor growth significantly compared with the DC vaccine; however, the tumor inhibition by AFP/IL-2-DC vaccine was the most potent." (PMID 23170121, 2012). "For this protein to be excreted in levels high enough to act as an antitumour agent, ways must be developed which would either allow increased TNF-α production at the tumour site or utilized the synergistic effect of interleukin-2 and TNF-α." (PMID 22737166, 2012). "It was discovered relatively early that IL-2 enhances the production of cytotoxic lymphocytes which are capable of lysing tumor cells while leaving normal cells unharmed." (PMID 22778725, 2012). "The tumor-targeted IL12-IL2 fusion protein was superior in activating resting T cells to amplify and secrete pro-inflammatory cytokines compared to targeted IL2 or IL12 alone." (PMID 23028547, 2012). "Dextran extravasation within tumor sites was selectively enhanced an interleukin-2 (IL-2) peptide fragment or vascular endothelial growth factor (VEGF)." (PMID 22479438, 2012). "A recent study reported that IL-2 regulates the balance between tumor Treg and Th17 cells by stimulating the differentiation of the former and inhibiting that of the latter in the tumor microenvironment." (PMID 22693525, 2012). "Peripheral blood contains LT precursors that have the ability to recognize tumour antigens and that send out an activation signal to the LTh cells and to the cytotoxic T lymphocytes (LTc) via cytokines IL-2." (PMID 23346250, 2012). "The response to IL2 and tumor-lysate (as nominal antigen) was more strongly affected than the response to the polyclonal T cell stimulus ConA." (PMID 23190502, 2012). "While Interleukin 2 has similar clinical tumor response rates as chemotherapy, it has shown to significantly improve survival while standard chemotherapy hasn’t." (PMID 29147288, 2012). "In parallel, IL-2 co-administration with cetuximab significantly inhibited MPM tumor growth in our model." (PMID 22922885, 2012). "Correspondently, the growth of the tumor was significantly inhibited by the treatment which was demonstrated by the decreased tumor weight while IL-2 and resveratrol co-treatment can exert the maximal inhibitory effects on the tumor growth." (PMID 22532866, 2012). "Most importantly, combination of MRF/magnetic field and anti-CD40/IL2 resulted in significantly greater inhibition of both primary and contralateral-tumor growth." (PMID 23133545, 2012). "In summary, these data reveal that expression of the OX40 co-stimulatory molecule is controlled by a combined TCR/gc cytokine-dependent mechanism and that dual anti-OX40/IL-2 therapy was able to greatly augment tumor immunotherapy." (PMID 22496812, 2012). "Another T-cell-based approach for immunotherapy in cancer includes TILs, which can be directly isolated from tumor tissue and expanded in vitro with IL-2." (PMID 23193418, 2012).
tumor (continued). "The tumor-bearing mice injected with NKG2D-Fc-IL2 showed significant luciferase activity at the tumor loci." (PMID 22509395, 2012). "The metastasis and tumor growth in lungs (seen as black nodules) were significantly inhibited by IL-2 or IL2+resveratrol co-treatment." (PMID 22532866, 2012). "This inhibitory effect of cetuximab alone and its enhancement by the addition of IL-2 was confirmed by quantitative measurements of the tumor area using Scion Image Software." (PMID 22922885, 2012). "For example, radiation therapy (RT) particularly when localized to the tumor mass, given alone or in combination with immunostimulatory cytokines (IL-2 and TNFα) enhances its efficacy by generating anti-tumor specific CTL responses." (PMID 22849661, 2012). "By contrast, when this vaccine antigen preparation was administered together with the multiple TLR agonist BCG plus IL-2, an inhibition of tumor growth was noted (G6)." (PMID 24955288, 2012). "Next, we tested the extent to which combined anti-OX40/IL-2 therapy would affect tumor growth and boost tumor immunotherapy." (PMID 22496812, 2012). "Of all cytokines tested in several experimental tumor models, IL-2 and IL-12 seem to have the strongest antitumor activity." (PMID 22220169, 2012). "In humans, administration of an IL-2 immunotoxin to tumor patients results in decreased numbers of Treg cells and higher responses against simultaneously administered tumor peptides." (PMID 22276195, 2012). "This expansion of Treg cells post administration of IL-2 can potentially hinder an immune response towards co-administered anti-tumor reagents and should therefore be avoided when planning new cancer immunotherapy protocols." (PMID 22276195, 2012). "TILs from lung cancer patients present poor cytolytic activity against autologous tumor cells, which is recovered after treating T-cells with recombinant IL-2." (PMID 23118782, 2012). "Mouse efficacy studies in SCID mice engrafted with disseminated lymphoma showed very high anti-tumor activity that was more than 50-fold more potent than that of rituximab, or the combination of rituximab and IL2." (PMID 24634778, 2012). "Interleukin-2 (IL-2) has been shown to promote tumor-specific T-cell proliferation and differentiation but systemic administration of IL-2 results in significant toxicity." (PMID 22509395, 2012). "Recently, viral vectors expressing feline or human IL2, respectively, were administered to domestic cats and it was shown a 33% reduction of tumor recurrences in cats receiving either human IL2 or feline IL2." (PMID 22666387, 2012). "More importantly, TC-1 tumor-bearing mice treated with a therapeutic HPV type 16 E7 DNA vaccine and then given the DNA construct encoding the chimeric NKG2D-Fc-IL2 protein demonstrated reduced tumor mass growth and prolonged survival." (PMID 22509395, 2012). "Exogenous treatment with recombinant TNF and IL2 have had success in mitigating tumor progression in a number of diseases." (PMID 22536907, 2012). "All patients received up to 5 cycles intranodal vaccination with autologous tumor lysate pulsed dendritic cells combined with high dose IL-2 and IFN-alpha." (PMID 23118856, 2012). "One potential concern with the delivery of IL-2 to the tumor loci is the expansion of regulatory T (Treg) cells." (PMID 22509395, 2012). "Identifying surface molecules that are specifically expressed in tumor cells but not in normal cells will be useful for the specific delivery of IL-2 to the tumor loci." (PMID 22509395, 2012). "Administration of IL-2 and/or gp10025-33 peptide pulsed dendritic cell vaccine (gp10025-33/DC) supports the expansion and anti-tumor activity of administered Pmel-1 T cells." (PMID 22713761, 2012). "The NKG2D-Fc system also allows us to deliver other immune-modulating or anti-cancer molecules (i.e., other than IL-2) to the tumor loci with the added benefit of reduced toxicity because of its specific targeting capabilities." (PMID 22509395, 2012).
tumor (continued). "Considering the important role of CD4+ in tumor immunotherapy, an IL-2 ELISPOT assay was employed to examine the CD4+ T cell response triggered by this immunization strategy." (PMID 23139820, 2012). "This differs from recovery of late effector TIL functions previously observed that required the presence of IL-2, Thus, the disruption of the tumor microenvironment was sufficient to allow the recovery of a Ca response in TIL." (PMID 21408177, 2011). "aAPCs can be used to expand long-term, IL-2 cultured TIL cultures as well as generate less differentiated "young" TIL cultures with tumor-reactivity via direct expansion from enzyme-digested tumors." (PMID 21827675, 2011). "For example, a short 2-day treatment of low-dose IL-2 resulted in a decrease in tumor load and an increase in survival, whereas the longer administration of IL-2 promoted CD8 T cell growth." (PMID 20953429, 2011). "Evidence from preclinical models additionally suggests that IL-2 therapy generates long-lasting immune surveillance, which is capable of eliminating tumor cells both inside and outside the CNS." (PMID 22190972, 2011). "Other members of the IL-2-related cytokine family are under intense investigation for additional anti-tumor applications based on encouraging murine tumor models." (PMID 24213115, 2011). "In summary, the combination of zoledronate and IL-2 generates large numbers of Vγ9Vδ2 T cells in vitro with cytotoxic activities against a range of tumour types, even in heavily pretreated patients with advanced malignancy." (PMID 21847128, 2011). "A similar approach to incorporate cytokines into vaccine therapy has been to transfect tumor cells used in vaccination with the gene for cytokines such as IL-2 or GM-CSF to localize the cytokine effects to the sites of tumor and T cell activation." (PMID 24213115, 2011). "Long-term culture of tumor-derived T cells in high-dose interleukin-2 (IL-2) allows for the generation of high numbers of TILs (>1 × 1011) but with preferential expansion of CD4+ lymphocytes." (PMID 21827675, 2011). "The fiber-modified adenovirus can be used as a vector for theefficient gene delivery of interleukin-2 to human normal and tumor hematopoieticcells." (PMID 22649700, 2011). "This likely reflects the use of TIL cultures established from tumor fragments or digests over 3-4 weeks in IL-2, which has been shown to promote TIL differentiation, telomere shortening and senescence." (PMID 21827675, 2011). "NK cells expanded in such manner lysed a significantly higher number of tumor cells (K562) in the presence of IL-2 than NK cells stimulated with IL-2 or IL-15 alone." (PMID 24212958, 2011). "The lack of IL-2 gene expression in cultured ALCL cells led us to search for an alternative source of IL-2 within the tumor site." (PMID 23675235, 2011). "For example, human tumor-derived exosomes were found to selectively impair the IL-2 response to cytotoxic effector cells while supporting Treg cell activities through a TGF-β-dependent mechanism." (PMID 22190973, 2011). "In this system local IL-2 delivery through the fusion molecule resulted in enhanced effector T cell responses and increased tumor cell lysis compared to systemic IL-2 delivery." (PMID 24213115, 2011). "Moxibustion also inhibited the growth of tumor and enhanced cellular immune functions via cytokine production (IL-2 or IL-12) and increase of natural killer cell activity in tumor-bearing mice." (PMID 20374659, 2010). "The staining for human IL-2 revealed a selective and comparable accumulation of the F16–IL2 immunocytokine around tumour vascular structures in both subcutaneous (A) and intracranial (B) xenografts." (PMID 20736949, 2010). "Splenic T cells from naïve mice were primed ex vivo with DC-Ad-MAGE-1 in the presence of IL-2 and IL-7 to elicit cytolytic reactivity against tumor cells." (PMID 20420712, 2010). "Immunotherapy using interferon (IFN)-α and/or interleukin (IL)-2 has shown promising anti-tumor activity in RCC." (PMID 21253521, 2010).
tumor (continued). "All long-term surviving mice following treatment with three doses of Tri-mAb alone or combination with IL-2 were resistant to tumor rechallenge, thereby demonstrating immunological memory against tumor." (PMID 20426873, 2010). "We have previously shown that transfection of HLA-E down-regulates the cytolytic response of TKD/IL-2-activated NK cells against tumor cells." (PMID 21179573, 2010). "We have previously shown that TKD/IL-2-activated NK cells kill their tumor target cells via a perforin-independent, granzyme B mediated lysis." (PMID 21179573, 2010). "Mouse models showed that early effector T cells mediate better anti-tumor response than intermediate and late effector T cells due to their high proliferative and survival potential and their ability to secrete IL-2." (PMID 21234353, 2010). "We also analyzed the ability of TyrTCR Tregs to influence cytokine production (e.g. IFN-γ, IL-2, and IL-10) when co-incubated with a tumor infiltrating cell line (TIL1235) and peptide pulsed APCs." (PMID 20668510, 2010). "In a multicenter trial, combination of tumor infiltrating lymphocytes with low dose IL-2 was compared with IL-2 alone." (PMID 20877591, 2010). "Coadministration of IL-2 has long been known to enhance immunotherapies such as adoptive transfer of tumor-specific T cells." (PMID 20426873, 2010). "A DNA vaccine expressing PSA induced PSA-specific CTLs when coinjected with the costimulatory cytokines IL-2 and GM-CSF and protected the majority of immunized mice against a lethal tumor challenge." (PMID 21197271, 2010). "Our group has previously shown that, surprisingly, the therapeutic effect of IL2-based immunocytokines against murine tumours is identical in immunocompetent and immunocompromised mice, and that NK cells are mainly responsible for the therapeutic action." (PMID 20736949, 2010). "In their study, effector memory T cells were reactivated and then infused into a sublethaly irradiated tumor-bearing host followed by systemic treatment of the mice with IL-2." (PMID 20543982, 2010). "To gain insight into the mechanism of the increased anti-tumor activity resulting from inclusion of IL-2 in therapy, we determined the relative proportions of activated T cells in tumor-draining lymph nodes." (PMID 20426873, 2010). "It has been published that secretion of IFN-gamma and IL-2 plays an important role for a long lasting anti-tumor response of modified T cells." (PMID 20815894, 2010). "Rosenberg and his associates have shown that lymphocytes from soft tissue metastases are an excellent source for TIL, which are more potent tumor killers than LAK cells when treated with interleukin-2 (IL-2)." (PMID 24281039, 2010). "The predictable effect of IL2-based immunocytokines in immunocompetent patients would be broader and stronger in tumour suppression, because of the involvement of T-cell and B-cell activation." (PMID 20736949, 2010). "TIL single-cell suspension was generated by the enzymatic digestion of the entire tumor and expanded in a high concentration of IL-2." (PMID 21234353, 2010). "Interleukin-2, interferon alpha, tumor-infiltrating lymphocytes, bacillus Calmette-Guerin, irradiated allogeneic tumor cells and monoclonal antibodies can be used." (PMID 21629531, 2010). "In addition, IL-2 has been implicated in eliminating self-reactive T cells by a process known as activation-induced cell death, which may obscure the antitumor effects of T lymphocytes produced within the tumor microenvironment." (PMID 20936120, 2010). "The culturing of NK cells in the presence of IL-2 generates lymphokine-activated killer cells, which, in conjunction with CTLs, are capable of mounting an aggressive immune response to tumor cells." (PMID 20936120, 2010). "There was a survival advantage of 15 months in those patients receiving tumor infiltrating lymphocytes and interleukin 2 (IL-2)." (PMID 20877591, 2010).